SCD (stearoyl-CoA desaturase)
Diseases named in the same sentence as SCD in open-access papers (continued):
Sharing a sentence is not in itself a finding about the gene and the disease.
cancer (continued). "SCD is recognised to facilitate cancer stemness and has been shown to be regulated by let-7a." (PMID 34944852, 2021). "Therefore, we were intrigued to find that in addition to monoallelic deletion, the SCD locus also undergoes unexpected hypermethylation and silencing in a subset of cancer cells." (PMID 33568479, 2021). "Because SCD is overexpressed in several cancers (as shown in fig." (PMID 33568479, 2021). "However, not all cancer cells are responsive to SCD inhibition, and a recent study demonstrated FADS2 as an alternative desaturation pathway in SCD-independent cancer cells." (PMID 37849907, 2021). "For example, we found SCD copy number loss in >90% of PTEN hemizygous loss (shallow) cancers, while no change in PTEN intact cancers (C); P < 0.001." (PMID 33568479, 2021). "SCD is often up-regulated and a therapeutic target in cancer." (PMID 33568479, 2021). "Although SCD-1 expression is frequently upregulated in cancer, this is an oxygen-dependent enzyme, which is inactivated under hypoxic conditions, a situation frequently observed in cancer." (PMID 33339398, 2020). "The transcription regulation of SCD-1 in cancer cells is complex and is a context-dependent event." (PMID 32630668, 2020). "Finally, in other cancers, SCD expression also positively correlates with the proliferation index, which is a factor associated with the lower survival of GBM patients." (PMID 32392704, 2020). "In this study, we determined whether the cell fate control of shear force stimulation is through regulating the SCD-1 expression in cancer cells." (PMID 32630668, 2020). "A recent study found that cancer cells can bypass SCD by using FADS2 for fatty acid desaturation." (PMID 32103057, 2020). "SCD is also important for cancer cell survival in metabolically compromised environments." (PMID 31517566, 2020). "SCD-1 is thought to play an important role in cancer progression." (PMID 31222099, 2019). "Thus, the existence of an alternative desaturation pathway provides cancer cells with an increased metabolic plasticity, especially upon SCD inhibition." (PMID 31284458, 2019). "Cancer cells are characterized by aberrant activation of lipid biosynthesis, producing saturated fatty acids and monounsaturated fatty acids via stearoyl-CoA desaturases (SCD) for regulating metabolic and signaling platforms." (PMID 31019378, 2019). "There is growing evidence of unbalanced levels of SFAs and MUFAs in the blood and tissues of cancer patients, which may indicate abnormal SCD activity in the disease." (PMID 30592142, 2019). "Available evidence points to a link between various cancer types and SCD-1 expression." (PMID 30684960, 2019). "Stearoyl-CoA desaturase 1 gene (SCD1) is highly overexpressed in many human cancers." (PMID 29396722, 2018). "SCD may be part of the physiological proliferation machinery in normal and cancer cells to provide the appropriate level of MUFA to growing cells." (PMID 28286737, 2017). "SCD is known as the key enzyme in regulation of membrane fluidity and carbohydrate metabolism that fuels tumor growth, increases energetic capacity and invasive and migratory properties of cancer cells." (PMID 27549611, 2016). "To confirm that the loss in cell number after treatment with siRNA and SCDi against SCD was indeed due to reduced availability of mono-unsaturated FAs, we reasoned that supplementing cancer cells with oleic acid, the enzymatic product of the SCD reaction, would rescue cell survival." (PMID 27042297, 2016). "Together, these results indicate that SCD is an important node in the metabolism of cancer cells and that inhibition of this enzyme could provide a successful strategy for cancer treatment." (PMID 27042297, 2016). "Furthermore, SCD was required for the generation of poly-unsaturated lipids in cancer cells grown in spheroid cultures, which resemble those found in tumour tissue." (PMID 27042297, 2016).
cancer (continued). "Interestingly, this activity was seen at a concentration of the drug that was ineffective at inhibiting cell growth in 2D cultures in full serum, suggesting that spheroid culture sensitises cancer cells towards SCD inhibition." (PMID 27042297, 2016). "Moreover, SCD inhibition sensitised cancer cells towards metformin and rotenone, two inhibitors of complex I of the respiratory chain." (PMID 27042297, 2016). ", we also analysed the effect of SCD inhibition on oxygen consumption in cancer cells." (PMID 27042297, 2016). "We also investigated whether attenuation of SCD activity also increases the sensitivity of cancer cells towards drugs that induce apoptosis via the mitochondrial death pathway." (PMID 27042297, 2016). "Moreover, we identified genes involved in cancer metabolic pathways, such as SCD and PAPSS2, in the tumor samples with EMT positive status." (PMID 27549611, 2016). "It should be noted that the RNAi strategy used here selectively targets SCD only in cancer cells." (PMID 27042297, 2016). "Our data implicate lipid desaturation as an essential process for cancer cell survival and suggest that targeting SCD could efficiently limit tumour expansion, especially under the metabolically compromised conditions of the tumour microenvironment." (PMID 27042297, 2016). "To investigate SCD expression in cancer, we queried published datasets of human cancer." (PMID 27042297, 2016). "Our study provides additional evidence for the important role of SCD in cancer." (PMID 27042297, 2016). "SCD-1 was found to be constitutively expressed in several human cancers." (PMID 25605240, 2015). "Although several lipogenic TFs, such as SREBFs and PPARs, have been implicated in the regulation of SCD expression, it is not clear how SCD is regulated under stress as well as in cancer." (PMID 25790137, 2015). "Changes in lipid desaturation mediated by altered SCD expression could affect membrane fluidity and contribute to the induction of cancer cell migration, a process that is also regulated by hypoxia." (PMID 24203995, 2013). "Inhibition of SCD can also impair cancer cell proliferation by activating AMPK." (PMID 24203995, 2013). "Furthermore, in cancer cells in which SCD activity was pharmacologically blocked, addition of n-9 or n-7 MUFA were equally effective in restoring the cell proliferation rate, indicating that all MUFA exhibit pro-growth and pro-survival functions." (PMID 22745828, 2012). "Recent studies indicate that changing levels of SCD activity may have significant implications in the response of cancer cells to stimuli that activate mitogenic and survival signaling pathways." (PMID 24212819, 2011). "The strong correlation of high levels of monounsaturated fatty acids and neoplastic phenotype may suggest that the regulation of stearoyl-CoA desaturase must play a role in cancer development." (PMID 21052495, 2010). "The incubation with the SCD inhibitor also resulted in a profound reduction (∼60%) in the incorporation of [3H]thymidine into newly synthesized DNA, an early marker of cellular proliferation rate, in both A549 and H1299 cancer cell lines." (PMID 19710915, 2009). "Thus, we incubated A549, H1299 and H460 cells with increasing concentrations of the SCD inhibitor for 24 h and found a progressive decrease in the rate of cell replication of cancer cells with respect to vehicle (DMSO)-treated cells." (PMID 19710915, 2009). "Stearoyl‐CoA desaturase (SCD), a critical enzyme controlling fatty acid desaturation, catalyses the production of lipids essential for maintaining membrane fluidity and cellular signalling, and aberrant SCD activity has been implicated in promoting CSC properties in various cancers." (PMID 41383134, 2025).
cancer (continued). "Memorial Sloan Kettering Cancer Center has made the initial discovery that cancer cells harboring mutations in the PI3K-AKT signaling pathway have been shown to develop resistance to ferroptosis, attributed to the upregulation of the SREBP1/SCD protein complex, which governs fatty acid synthesis." (PMID 40535804, 2025). "Therefore, for these types of cancer, only the combination therapy of SCD inhibitors and FADS2 inhibitors can block all compensatory pathways for tumor cells to acquire desaturated FAs, leading to impaired proliferation of tumor cells both in vitro and in vivo." (PMID 41421797, 2025). "In addition, SCD has potential as a prognostic marker in various cancers and may aid in overcoming drug resistance." (PMID 39351232, 2024). "Moreover, our findings establish that the S-HFD, along with an SCD inhibitor, exerted the most potent antiproliferative effects by accumulating stearate and limiting oleate in mice harboring xenografts derived from various cancer cell lines." (PMID 39617788, 2024). "Moreover, due to the dependency of cancer cells on SCD and other lipogenic enzymes, these factors are not only regulated by cell intrinsic determinants, but also by the specific conditions of the tumour environment, for example the availability of oxygen and external sources of unsaturated lipids." (PMID 39009641, 2024). "RCC is also characterized by significant accumulations of polyunsaturated fatty acids in association with increased expression of stearoyl-CoA desaturase (SCD1) and FA elongase 2 and 5, as well as metabolic heterogeneity that may allow for subtyping of cancers and prediction of clinical outcomes." (PMID 36902045, 2023). "Therefore, SCD is considered a novel potential target in cancer therapy." (PMID 35406721, 2022). "Dietaries involving caloric restriction and a ketogenic diet could impair SCD activity in cancer." (PMID 35646898, 2022). "Based on the expression of these three genes, the cancer cell clusters could be subdivided into SCD high [SCD-Hi (SC 6)], FADS2 high [FADS2-Hi (SC 17)], FASN high [FASN-Hi (SC 11)], SCD/FADS2/FASN high, [Triple-Hi (SC 7)] and SCD/FADS2/FASN low [Triple-low (SC 8)] cancer cells." (PMID 36338708, 2022). "However, dietary oleate cannot fully compensate for the lack of de novo SCD activity since both genetic and pharmacological inhibition of SCD in mice alters membrane lipid composition and are consequential in both normal physiology and pathology including cancer." (PMID 33568479, 2021). "Moreover, a possibility has been further proposed that SCD-1 activity inhibition could become a potential target of anti-cancer therapy." (PMID 32630668, 2020). "An increase in the expression of stearoyl-CoA desaturase 1 (SCD1), the enzyme that converts saturated fatty acids to ∆9-monounsaturated fatty acids, has been observed in a wide range of cancer cells, and this increase is correlated with cancer aggressiveness and poor outcomes for patients." (PMID 31284458, 2019). "Indeed, enzymes within the Fatty Acid (FA) synthesis pathway, such as Acetyl-coA-A Lyase (ACLY), Acetyl-CoA-A Carboxylase (ACC) and Stearoyl-CoA desaturase-1 (SCD-1) have been targets of pharmacological inhibitors in an attempt to decrease their effect on cancer cell proliferation." (PMID 28452935, 2017). "Thus, again, it seems that pharmaceuticals capable of increasing the fatty acid desaturation index in rapidly proliferating cancer cells by elevating SCD activity may have high anti-tumor potential." (PMID 26636650, 2016). "Another implication of the present study is that it might be important to completely inhibit SCD activity in human cancer cells in order to achieve sufficient tumor growth inhibition in vivo, whereas a partial SCD inhibitor might have limited therapeutic efficacy." (PMID 24069385, 2013).
cancer (continued). "Stearoyl-CoA desaturase (SCD) catalyzes the introduction of a double bond at the C9 position of short-chain FAs (mainly converting stearoyl-CoA into oleoyl-CoA), and the inhibition of SCD function may lead to cell death in cancer cells by inducing the accumulation of unsaturated FAs." (PMID 40137165, 2025). "Some studies suggest that oleic acid induced cancer cells led to increase the expression of SREBP1, FAS, and SCD‐1 and induce tumor progression in hepatocarcinoma cells." (PMID 39425259, 2025). "SCD and FADS2 are pivotal enzymes within the fatty acid desaturation pathway and are markedly expressed in various cancer types." (PMID 40535804, 2025). "While most studies have focused on inhibiting SCD, several recent studies have focused on blocking other FADS in cancer." (PMID 40055794, 2025). "Several enzymes involved in de novo fatty acid synthesis, including FASN, ACLY, SCD, and ACSS2, are abnormally expressed in various cancers, promoting fatty acid synthesis and contributing to malignant tumor phenotypes." (PMID 41285764, 2025). "Recent evidence suggests that, besides SCD enzymes, FADS2 also plays a role in FA desaturation, and cancer cells utilize a FADS2-dependent alternative pathway to transfer palmitate to sapienate to support cell proliferation." (PMID 40814339, 2025). "Zeb1-binding regions were associated with an active, open (FADS2) or inactive, closed (SCD and FASN) chromatin state in Zeb1high-expressing cancer cells, and an inverse pattern in Zeb1-depleted cells." (PMID 39009641, 2024). "Re-examination using an alternative online tool, GEPIA, confirmed these findings, indicating an upregulation of SCD expression in PRAD and other cancers." (PMID 39351232, 2024). "In colon tumor cells, inhibition of AhR activity decreases the expression levels of SCD-1, a key enzyme of the biosynthetic pathway, and SREBP, a transcriptional regulator of adipogenesis, to restrict cancer cell proliferation in a cell-specific manner." (PMID 38434684, 2024). "The results showed that SCD was significantly upregulated in BRCA patients aged 80–100 years, in individuals with stage 4 cancer, and in the Asian race." (PMID 38905386, 2024). "It was revealed that SCD expression was upregulated in 24 types of tumors compared to adjacent normal tissues, including PRAD and several other cancer types." (PMID 39351232, 2024). "Pharmacological inhibition of selected lipogenic enzymes (SCD and FADS2) allows the manipulation of ferroptosis sensitivity preferentially in high-Zeb1-expressing cancer cells." (PMID 39009641, 2024). "Lipid metabolic pathways, including FASN and stearoyl-CoA desaturase (SCD) signaling, also play pivotal roles in maintaining cancer stem cell (CSC) populations, thereby driving metastasis and drug resistance in HCC." (PMID 39610917, 2024). "The GEPIA, University of ALabama at Birmingham Cancer data analysis Portal (UALCAN), TNMplot, and TCGA databases analyzed that the expression of SCD in CC tissue is higher than that in normal tissue and directly related to bad prognosis." (PMID 38355626, 2024). "The prognostic ability of SCD and FADS2 expression in pan-cancer was evaluated using GEPIA database." (PMID 38905386, 2024). "Combined with bioinformatic analyses, our functional studies clearly indicate that targeting SCD is a promising strategy for combating PRAD, as has been extensively reported in cases of other cancers." (PMID 39351232, 2024). "These cancer cells develop de novo FA synthesis with increased activity of multiple lipogenic enzymes, ACC, ACLY, CoA carboxylase (ACACA), and SCD." (PMID 39332525, 2024). "However, it must be noted that certain cancer cells utilize an alternative pathway for FA desaturation and sapienate biosynthesis, bypassing the established SCD-dependent pathway and diminishing the relevance of SCD, thereby questioning its suitability as a therapeutic target." (PMID 38994204, 2024).
cancer (continued). "ACLY, FASN, SCD, and ACC are considered key enzymes for fatty acid synthesis and have been reported to promote proliferation in several types of cancers." (PMID 37821935, 2023). "In accordance with the abnormal expression of SCD, an unbalanced amount of SFA and MUFA has been observed in blood and tissue samples from cancer patients." (PMID 37373069, 2023). "We did not provide direct in vivo experiment results to uncover the detailed mechanisms of CPT1A, SCD and FASN over-expression stimulating cancer cell proliferation and metastases." (PMID 38003694, 2023). "SCD, an enzyme that catalyzes the rate-limiting step in MUFA synthesis, is upregulated under stress in cancer cells." (PMID 37051693, 2023). "SCD also stimulates the Wnt signaling pathway and YAP activation in support of tumorigenesis and facilitates metabolic reprogramming in cancer mediated by the regulation of AKT, AMPK, and NF-κB via MUFAs." (PMID 38003694, 2023). "In a variety of cancer types, a considerable number of drugs that can inhibit the synthesis of SREBP, ACLY, ACC, FASN, SCD, and PPARα have been tested for anticancer effects in preclinical and clinical studies." (PMID 38189049, 2023). "SCD-mediated lipogenesis is downstream of the PI3K–AKT–MTOR pathway, which suppresses ferroptosis in cancer cells." (PMID 37051693, 2023). "Concerning the relationship between SCD and AMPK, a study showed that inhibition of SCD1 in cancer cells promoted the activation of AMPK and the subsequent reduction of glucose-mediated lipogenesis." (PMID 35370706, 2022). "The gene expression levels of FASN, SCD and FADS2 were highly heterogeneous in GBM cancer cells and correlated with cell fate." (PMID 36338708, 2022). "A recent study demonstrated that stearoyl‐CoA desaturase‐1 (SCD1) and fatty acid binding protein (FABP4) play roles in tumor recurrence by reducing the sensitivity of cancer cells to ferroptosis." (PMID 36317423, 2022). "As C16:0 is the main product of FASN, cancer cells commonly co-overexpress FASN and SCD to maintain homeostatic levels of SFAs and MUFAs." (PMID 34983949, 2022). "Elevated levels of enzymes responsible for lipid elongation (ELOVL), monounsaturation (Stearoyl‐CoA Desaturases [SCD]), and polyunsaturation (fatty acid desaturases [FADS]) have been reported in other cancers." (PMID 35560527, 2022). "Strikingly, during SCD inhibition, other enzyme such as FA desaturase 2 (FADS2) was utilized by cancer cells to fulfil their requirements for MUFA." (PMID 35646898, 2022). "S100A2, TGFA, MET, PCNA, SCD, GDF15, and PAI1 act as oncogenes by promoting cancer metastasis or proliferation 24-30." (PMID 34131400, 2021). "In our study the target genes are PAPSS2, SCD, and ID4 which play significant roles in various cancers." (PMID 34721037, 2021). "MYC promotes metabolic reprogramming in cancer and is involved in lipogenesis by pronouncedly activating acetyl-CoA carboxylase (ACACA), fatty acid synthetase (FASN), and stearoyl-CoA desaturase (SCD)." (PMID 33791309, 2021). "Several key lipogenic enzymes, such as acetyl-CoA carboxylase (ACC), FA synthase (FASN), and stearoyl-CoA desaturase (Δ9) (SCD), participate in this process, and in cancer cells they are upregulated to increase de novo FA synthesis." (PMID 34722305, 2021). "Genetic and epigenetic mechanisms determine SCD inhibitor sensitivity and acquired resistance through FOSB in cancer." (PMID 33568479, 2021). "For example, upregulation of CEMIP, RRM2, LAMC2, SCD, TNS4, and PLAU in humans is prognostically unfavorable for various cancers; these genes have CR-upregulated mouse orthologs." (PMID 34202278, 2021).